TNFRSF6B (TNF receptor superfamily member 6b)
Description:
Soluble decoy receptor that binds and neutralizes the TNF-family ligands TNFSF14/LIGHT, TNFSF15, and FASLG, preventing them from interacting with their cognate receptors and thereby blocking apoptosis and other immune-signaling pathway.
Synonyms: DcR3; TR6; M68; DJ583P15.1.1; M68E
Tractability: Antibody: its Gene Ontology location is reachable by antibodies, with high confidence; UniProt places it where antibodies can reach, with medium confidence; UniProt predicts a signal peptide or a membrane-spanning region.
Gene: Protein-coding gene on chromosome 20 (63,696,368 to 63,698,689, forward strand). Ensembl gene ENSG00000243509.
Subcellular location: Secreted
Pathways (Reactome):
Immune System: TNFs bind their physiological receptors
Gene Ontology:
Molecular function: protein binding; receptor decoy activity
Biological process: negative regulation of apoptotic process; negative regulation of inflammatory response
Cellular component: decoy receptor complex; extracellular region; membrane
Genetic constraint (gnomAD): Loss-of-function variants: 24 observed, 17.27 expected, observed/expected ratio (o/e) 1.39, 90% interval 1 to 1.86. The synonymous counts are far from expectation, so gnomAD's model fits this gene poorly and the ratio says little. Missense variants: 544 observed, 393.6 expected, observed/expected ratio (o/e) 1.38, 90% interval 1.29 to 1.48. Synonymous variants: 279 observed, 174.96 expected, observed/expected ratio (o/e) 1.59, 90% interval 1.45 to 1.76.
Homologues: Orthologues: chimpanzee TNFRSF6B (97% identical), macaque TNFRSF6B (91% identical), dog TNFRSF6B (73% identical). Paralogues in human: TNFRSF11B (29% identical), TNFRSF21 (23% identical), LTBR (21% identical), TNFRSF1B (21% identical), TNFRSF14 (20% identical), TNFRSF8 (20% identical), TNFRSF4 (19% identical), TNFRSF11A (18% identical), NGFR (18% identical), RELT (17% identical), TNFRSF1A (17% identical), CD40 (16% identical), and 9 more.
Diseases named in the same sentence as TNFRSF6B in open-access papers:
TNFRSF6B is named in the same sentence as 109 diseases in open-access papers, as found by Europe PMC text mining. Sharing a sentence is not in itself a finding about the gene and the disease. The quoted sentences say what the papers report.
pancreatic cancer (17 papers, 2011 to 2024). "We have previously shown that RON P5P6 isoform is oncogenic, TNFRSF6B (DcR3 protein) prevents TRAIL induced apoptosis and GDF15 (MIC-1 protein) is being investigated as a highly specific marker of pancreatic cancer." (PMID 27323855, 2016).
gastric cancer (13 papers, 2010 to 2023). A primary or metastatic malignant neoplasm involving the stomach. "In both colon and gastric cancers, TNFRSF6b induces EMT via various signaling pathways and affects the growth and metastasis potential in colon carcinoma." (PMID 37719017, 2023). "TNFRSF6B, that may inhibit apoptosis and promote cell survival, is over-expressed in gastrointestinal tract tumors, colorectal carcinoma and gastric cancer." (PMID 24165089, 2013). "These amplifications have been seen in prior studies in gastric cancer along with amplification of 20p for which ZNF217 and TNFRSF6B have been suggested as candidate driver genes." (PMID 21781349, 2011).
Sepsis (13 papers, 2015 to 2026). Sepsis is defined as life-threatening organ dysfunction caused by a dysregulated host response to infection. "TNFRSF6B was suggested as a biomarker for pathogen-derived inflammation, as it plays an important role in sepsis pathogenicity in humans." (PMID 36213116, 2022).
colon carcinoma (12 papers, 2010 to 2023). "TOP1 higher expression was shown to be associated with breast cancer, where it is a predictor of poor prognosis, but its role in colon cancer has not been established Antibody neutralization of TNFRSF6B in hepatocellular carcinoma cell lines inhibited proliferation and induced apoptosis." (PMID 22879877, 2012).
glioma (11 papers, 2014 to 2023). A benign or malignant brain and spinal cord tumor that arises from glial cells (astrocytes, oligodendrocytes, ependymal cells). "Ten shared SNPs near TNFRSF6B (20q13.33) are associated with IBD, CD, glioma and atopic dermatitis; this regions is associated with UC, glioblastoma, prostate cancer and lung function." (PMID 29309429, 2018).
colorectal cancer (10 papers, 2013 to 2024). A primary or metastatic malignant neoplasm that affects the colon or rectum. "Finally, we obtained four TNFRSF6B-related GWAS risk SNPs in the gene’s adjacent super-enhancer regions from the ‘colorectal cancer’ phenotype." (PMID 37207350, 2023).
ovarian carcinoma (10 papers, 2010 to 2020). A malignant neoplasm originating from the surface ovarian epithelium. "In a subsequent cohort study, we will compare the survival rate of two groups of ovarian cancer patients (high TNFRSF6B expression and low TNFRSF6B expression), and the exact mechanism by which the TNF-α/TNFRSF6B signaling pathway inhibits ovarian cancer." (PMID 33083827, 2020). "We believe that TNFRSF6B is a tumor suppressor in ovarian cancer." (PMID 33083827, 2020).
breast carcinoma (8 papers, 2012 to 2022). "TNFRSF6B itself can attenuate inflammation and overexpression of this proteins has been related to breast cancer progression." (PMID 35432372, 2022).
glioblastoma (7 papers, 2010 to 2021). The most malignant astrocytic tumor (WHO grade IV). "DDX6 is involved in radio- and chemoresistance in glioblastoma, and TNFRSF6B suppresses CD95 ligand-induced apoptosis and chemotaxis in malignant glioma." (PMID 33936159, 2021).
inflammatory bowel disease (5 papers, 2015 to 2026). A spectrum of small and large bowel inflammatory diseases of unknown etiology. "TNFRSF6B and SULT1A1 colocalised with inflammatory bowel disease, and TNFRSF6B also separately colocalised with its two main forms: Crohn’s disease and ulcerative colitis." (PMID 38565889, 2024).
multiple myeloma (5 papers, 2013 to 2023). "The proteome analyses of the same SCDCLs identified two pivotal proteins in the extracted protein signature, i.e., (i) BRD3 which is a family member of the BET proteins and (ii) the TNF receptor TNFRSF6B whose gene possess a super-enhancer in multiple myeloma cells." (PMID 37719017, 2023).
Crohn disease (4 papers, 2017 to 2024). A gastrointestinal disorder characterized by chronic inflammation involving all layers of the intestinal wall, noncaseating granulomas affecting the intestinal wall and regional lymph nodes, and transmural fibrosis. "An association was found between TNFRSF6B SNP with Crohn’s disease susceptibility." (PMID 36944972, 2023).
lung carcinoma (4 papers, 2010 to 2021). "Upregulated TNFRSF6B was identified in several human cancers including colon and lung cancers, and functioned as predictor of tumor invasion." (PMID 34404901, 2021).
allergic disease (2 papers, 2024). An immune response that occurs following re-exposure to an innocuous antigen, and that requires the presence of existing antibodies against that antigen. "In addition, ERBB3, IL1R1, IL1RL2, IL6R, LRRC32, STAT6, and TNFRSF6B have been strongly linked to allergic diseases, such as asthma and rhinitis." (PMID 38773393, 2024).
Arthritis (2 papers, 2020 to 2025). Inflammation of a joint. "Additionally, many of the other proteins have been indicated in arthritis or pain conditions such as VEGFR3, FGR, TNFRSF6B, FGF19, DKK3 and proteins belonging to CCL, MMP and CXCL families." (PMID 41170664, 2025).
atopic dermatitis (2 papers, 2018 to 2023). "TNFRSF6B is an anti-apoptotic gene, and serum levels of this protein are increased in patients with atopic dermatitis." (PMID 36719906, 2023).
epilepsy (2 papers, 2016 to 2024). A brain disorder characterized by episodes of abnormally increased neuronal discharge resulting in transient episodes of sensory or motor neurological dysfunction, or psychic dysfunction. "Other targets, such as the NFkB subunits and regulators or the decoy receptor of FAS, TNFRSF6B, whose gene upregulation has never been associated with epilepsy, should be investigated." (PMID 27006531, 2016). "We have not found any studies regarding the association between TNFRSF6B expression and epilepsy." (PMID 27006531, 2016).
systemic lupus erythematosus (2 papers, 2020 to 2026). An autoimmune multi-organ disease typically associated with vasculopathy and autoantibody production. "In systemic lupus erythematosus, elevated TNFRSF6B may be associated with enhanced T cell activation and plays a possible role by T cell hyperreactivity and apoptosis inhibition in activated T cells, which is similar to our findings." (PMID 33192575, 2020).
coccidiosis (1 paper, 2020). A parasitic infection caused by Coccidia. "In our study, TNFRSF6B promoted various proinflammatory cytokines expression and NO secretion, which may be the cause of intestinal inflammation injury caused by coccidiosis." (PMID 33192575, 2020). "The expression and secretion of multiple pro-inflammatory cytokines caused by TNFRSF6B upregulation may mediate inflammation in coccidiosis." (PMID 33192575, 2020). "Totally, we confirmed that TNFRSF6B can aggravate the inflammatory response in chicken coccidiosis by inhibiting Fas signal pathway." (PMID 33192575, 2020). "The TNFRSF6B-mediated upregulation of ROS level may also be another way of intestinal damage in coccidiosis." (PMID 33192575, 2020). "It was speculated that TNFRSF6B may participated in the immune response to chicken coccidiosis." (PMID 33192575, 2020). "As a member of Cytokine-cytokine receptor interaction pathway, also a kind of protein located in the surface of cell membrane, it was speculated that TNFRSF6B gene may participate in the immune response in coccidiosis and we assumed it was a potential candidate for subsequent research." (PMID 33192575, 2020). "Overall, our study indicates that TNFRSF6B upregulated in BAE, is capable of aggravating the inflammatory response by inhibiting macrophages apoptosis via downregulating Fas signal pathway, which may participate in host’s immune response to coccidiosis." (PMID 33192575, 2020). "Nevertheless, there is no literature about TNFRSF6B in coccidiosis." (PMID 33192575, 2020). "However, there is still no any report of TNFRSF6B in chicken coccidiosis." (PMID 33192575, 2020).
Lynch syndrome (1 paper, 2014). An autosomal dominant hereditary neoplastic syndrome characterized by the development of colorectal carcinoma and a high risk of developing endometrial carcinoma, gastric carcinoma, ovarian carcinoma, renal pelvis carcinoma, and small intestinal carcinoma. "Whole-genome DASL-based gene expression profiling based on 18.6 k genes identified 349 significantly deregulated genes with up-regulation of e.g. PTPRH, BIRC3, SHH and TNFRSF6B in Lynch syndrome tumors." (PMID 24848881, 2014).
mastitis (1 paper, 2022). Inflammation of breast tissue during lactation or postpartum due to an obstructed duct or infection. "In the case of the cytokine–cytokine-receptor interaction pathway, other genes, such as CD40, IL1RN, CXCR1, TNFRSF6B, and CCL19, were found to be involved in mastitis defense or immune response, as all these genes were upregulated in the mastitic cows based on their FC values." (PMID 35723402, 2022).
tumor (55 papers, 2010 to 2025). "In PDAC, TNFRSF6b also promotes proliferation and tumor growth and is associated with worse outcomes." (PMID 37719017, 2023). "TNFRSF6B is involved in the apoptosis pathway, but it can activate NF-κB to support tumor cell survival." (PMID 39223142, 2024). "After excluding TNFRSF6B, which had low expression in tumor and normal tissues, 59 costimulatory molecules were selected from the TCGA-COAD dataset." (PMID 36646765, 2023). "Oncogenes EIF4A2 and TNFRSF6B, which are overexpressed in tumours and described to inhibit apoptosis while promoting invasion and migration, were significantly downregulated alongside HuR and are suggestive of a pleiotropic effect." (PMID 37925433, 2023). "The overexpression of many other amplified genes (e.g., AURKA, HRH3, MIR646, MRGBP, PCK1, PMEPA1, SLCO4A1-AS1, SOX18, TNFRSF6B) is associated with PDAC cell proliferation and tumour growth." (PMID 36289850, 2022). "TNFRSF6B was overexpressed in ccRCC and could promote adhesion, migration, and invasiveness of tumor cells of ccRCC." (PMID 34537809, 2021). "The DEGs included genes involved in cell proliferation and migration (e.g., COL11A1), tumor‐promoting factors that degrade the extracellular matrix (e.g., MMP11), as well as immunosuppressive (TGFB1) and proinflammatory responses (TNFRSF6B, IFNGR2, GSDMB)." (PMID 40952312, 2025). "In particular, most of the amplified genes are involved in proliferation and tumour progression in PDAC, such as AURKA, HRH3, MIR646, MRGBP, PCK1, PMEPA1, SLCO4A1-AS1, SOX18, and TNFRSF6B." (PMID 36289850, 2022).
cancer (48 papers, 2005 to 2025). A tumor composed of atypical neoplastic, often pleomorphic cells that invade other tissues. "Aberrant expression of TNFRSF6B in cancer cells inhibited Fas-mediated and TNFRSF14-mediated apoptosis, leading the cancer cells to escape during the immune process." (PMID 33192575, 2020). "Additional functional data are needed to decipher the exact role of TNFRSF6B in regulating cancer recurrence, immune response to cancer and patients’ survival in UM." (PMID 30653520, 2019). "The 20q13.33 region overlapped with several cancer related genes such as CDH4, LAMA5, RPS21, KIAA1510, TNFRSF6B (M68, DcR3), RTEL, EEF1A2 and PTK6." (PMID 24165089, 2013).
infection (7 papers, 2018 to 2025). The state of being infected such as from the introduction of a foreign agent such as serum, vaccine, antigenic substance or organism. "The differentially expressed cytokines such as IL6, IL10, IL11, IL15, TNFSF10, TNFRSF6B and TNFAIP6 were detected in the lung of goats after Pm infection in this study." (PMID 35739866, 2022).
cutaneous disorder (2 papers, 2022 to 2025). "Notably, TNFRSF6B and CLEC16A, a less characterized gene in AD pathogenesis, have shown consistent associations with the disease across European and Asian ancestries, enhancing their critical role as immunomodulatory agents in the cutaneous disorder." (PMID 41009683, 2025).
neurological diseases (1 paper, 2025). "PheWAS analysis of TNFRSF6B revealed associations with multiple neurological diseases, highlighting its role in neuroinflammation regulation." (PMID 40529500, 2025). "TNFRSF6B had multiple loci with P-values surpassing the genome-wide significance threshold (-log10P = 8), indicating strong associations with neurological diseases." (PMID 40529500, 2025).
TNFRSF6B also shares sentences with these, for which no sentence is quoted: hepatocellular carcinoma (10 papers); autoimmune disease (6); lymph node metastasis (4); pancreatic adenocarcinoma (4); psoriasis (4); rheumatoid arthritis (4); acute respiratory distress syndrome (3); Autoimmunity (3); endometriosis (3); liver cirrhosis (3); prostate carcinoma (3); septic shock (3); Alzheimer disease (2); amyloid (2); asthma (2); bacterial meningitis (2); Cirrhosis (2); diabetes (2); experimental autoimmune encephalomyelitis (2); fungal infections (2); gout (2); idiopathic pulmonary fibrosis (2); lymphoma (2); malignant glioma (2); nasopharyngeal carcinoma (2); oral cancer (2); renal cell carcinoma (2); systemic inflammatory response syndrome (2); ulcerative colitis (2); viral infections (2).
A further 53 diseases each share a sentence with TNFRSF6B in 1 paper.